ATF5 (activating transcription factor 5)
Diseases named in the same sentence as ATF5 in open-access papers (continued):
Sharing a sentence is not in itself a finding about the gene and the disease.
breast carcinoma (14 papers, 2014 to 2025). "ATF5 is also essential for promoting tumor growth in mammary tumor cells in which ATF5 knockdown reduces the proliferation and migration of CD24+ Mvt1 cells." (PMID 35806136, 2022). "ATF5 itself has been related to cell enhanced invasion of fibrosarcoma and breast cancer cells, and its therapeutic targeting strongly reduced cancer cell survival, except for pancreatic cancer and CRC." (PMID 35008201, 2021). "Most of the work on ATF5 in relation to breast cancer has focused on ATF5-mediated promotion of cell survival, though studies have been conducted analyzing ATF5-mediated invasive characteristics." (PMID 29137451, 2017). "As CD24 expression is often associated with CD44 expression in breast cancer cells, we analyzed CD44 cell surface expression in Mvt1-derived scrambled and ATF5-KD cells." (PMID 28785242, 2017). "This study also reported that ATF5 is responsible for the transactivation of BCL-2 via an ATF5-specific regulatory element, and that this is predominantly responsible for the cell-type dependent antiapoptotic function of ATF5 in breast cancer." (PMID 29137451, 2017). "Further studies composed of in vivo and clinical studies would help better evaluate the role of ATF5 in regulating the invasive characteristics of breast cancers." (PMID 29137451, 2017). "The results of this study suggest that ATF5 plays a major role in promoting tumor growth of Mvt1 and Met1 mammary tumor cells." (PMID 28785242, 2017). "Further to the effects of ATF5 knockdown on mammary tumor cell proliferation, we show here that migration is also impaired in ATF5-KD Mvt1 and Met1 cells." (PMID 28785242, 2017). "Taken together, the results of the present study emphasize the role of ATF5 in enhancing mammary tumor cells proliferation, migration, and overall aggressiveness, thereby promoting mammary tumor growth." (PMID 28785242, 2017). "Here, we show for the first time that ATF5 is also upregulated after exposure to either insulin or IGF-I and suggest that the ATF5 can also mediate the proliferative effects of the two ligands, which can subsequently lead to an increased mammary tumor growth." (PMID 28785242, 2017). "Using the delivery of short hairpin RNA vectors into the Mvt1 and Met1 cell lines, we tested the role of ATF5 in the development of mammary tumors in vivo and in regulating proliferation and migration of these cells in vitro." (PMID 28785242, 2017). "Moreover, the authors showed that ATF5 expression was markedly increased in the invasive MDA-MB-231 cells than in the less invasive breast cancer cell line, MCF-7." (PMID 28785242, 2017). "The results of the present study suggest that breast cancer patients with CD24 cell surface expressing cancer cells may also benefit from anti-ATF5 therapy." (PMID 28785242, 2017). "Therefore, to our knowledge, we show here for the first time that ATF5 downregulation leads to a decreased mammary tumor growth in vivo." (PMID 28785242, 2017). "In contrast, the marked reduction in the activation of PI3K/Akt signaling pathway, as evidenced by decreased p-Akt levels, may indicate a reduced proliferation rate of ATF5-KD mammary tumor cells." (PMID 28785242, 2017). "In light of the important role of ATF5 in the regulation of proliferation, survival, migration, and overall aggressiveness of cancer cells, we sought to investigate the effects of ATF5 knockdown in Mvt1 and Met1 murine mammary tumor cell lines." (PMID 28785242, 2017). "Importantly, previous studies, investigating the role of ATF5 in survival of breast cancer cell lines, have focused so far on experiments performed in vitro, such as proliferation, migration, and apoptosis assays, and intracellular mechanisms by which ATF5 may exert its effects." (PMID 28785242, 2017). "Some members of this gene family are protective against breast cancer but others such as ATF4, ATF5, and CREB, promote breast cancer pathology." (PMID 24586334, 2014).
breast carcinoma (continued). "Repression of ATF5 induces apoptotic cell death in neural and breast cancer cells but does not kill non-transformed cells." (PMID 25682872, 2015). "Moreover, ATF5 is expressed at higher levels in neural and breast cancer cells than in the respective non-cancerous cells." (PMID 25682872, 2015).
malignant glioma (11 papers, 2010 to 2022). A grade III or grade IV glioma arising from the central nervous system. "However, to the best of our knowledge, no studies have shown that the anti-apoptotic effect of HCMV infection in malignant glioma is associated with ATF5." (PMID 25120656, 2014). "ATF5 then activates the transcription of the anti-apoptotic gene myeloid cell leukemia sequence 1 (MCL1) transcription by binding its promoter and increasing the malignant glioma survival through the CREB3L2/ATF5/MCL1 anti-apoptotic pathway." (PMID 35806136, 2022). "In malignant glioma, metastatic cells take advantage of survival signals triggered by ATF5 gene, which is essential to ignore anchorage-dependent and niche-dependent cell death signals." (PMID 34249670, 2021). "We also observed ATF5, a gene for which expression in malignant glioma is correlated with poor survival." (PMID 28166733, 2017). "ATF5 is essential in the genesis of malignant glioma, and analysis of human malignant glioma samples indicated that ATF5 expression inversely correlated with disease prognosis." (PMID 26943771, 2016). "A variety of observations have identified ATF5 as a potential target for treatment of malignant gliomas." (PMID 26863637, 2016). "ATF5, an anti-apoptotic factor, is highly expressed in malignant glioma and is important in the promotion of cell survival." (PMID 25120656, 2014). "Recent work has revealed an essential survival pathway mediated by ATF5 in malignant glioma; pharmacological inhibition of this pathway leads to tumor regression in mice." (PMID 21311102, 2010). "This approach identified 12 genes as regulators of ATF5 expression, and further analyses revealed the upstream signaling pathways that regulate ATF5 expression in malignant glioma." (PMID 21311102, 2010). "We generated a mouse malignant glioma GL261 cell line stably expressing the human DTR driven by the mouse ATF5 promoter; the ATF5 promoter is normally active in GL261 cells, which drives expression of the DTR gene and confers susceptibility to DT." (PMID 21311102, 2010). "BRAF-mutated melanoma cells, acquire resistance to vemurafenib by GCN2/ATF4 activation and overexpression of ATF5 conferred radioresistance in lung cancer cells and in malignant glioma cells, ATF5 promoted survival through transcription of anti-apoptotic MCL-1." (PMID 33782711, 2021). "Our findings thus identify Pen-d/n-ATF5-RP as a potential therapy for malignant gliomas." (PMID 26863637, 2016). "Although we focus here on malignant gliomas, it is significant to note that ATF5 is expressed by a wide variety of carcinomas, and that culture studies have shown apoptotic actions of d/n-ATF5 or ATF5 siRNA on tumor cells from a diverse range of tissues." (PMID 26863637, 2016). "Previous studies have shown that ATF5 is an important anti-apoptotic protein in malignant glioma." (PMID 25120656, 2014). "It was also described that, in malignant glioma, an FRS2/PAK1-activated RAS/MAPK signaling cascade up-regulates CREB3L2, which directly binds to the ATF5 promoter resulting in ATF5 transcription, an anti-apoptotic factor which plays a role in cell survival." (PMID 31334233, 2019). "ATF5 expression have been detected in brain tumors, and is particularly high in malignant glioma, while not been detected in mature astrocytes and brain neurons." (PMID 28473657, 2017). "Inhibition of other components of the ATF5-mediated survival pathway, including FGFR (using the specific inhibitor PD173074), EGFR (CL-387,785), RAS (manumycin A), MEK (U0126), ERK (FR180204) and PI3K (LY294002), also induces apoptosis in malignant glioma cells." (PMID 21311102, 2010).
hepatocellular carcinoma (9 papers, 2010 to 2026). A malignant tumor that arises from hepatocytes. "ATF5 can also be degraded through proteasome pathways specifically in hepatocellular carcinoma cells; several miRNAs, such as miR-141–3p, miR-520b-3p, and miR-134–5p, have been identified to bind to the 3’ UTR site of ATF5 mRNA and suppress ATF5 expression." (PMID 38706516, 2023). "NPM was shown to regulate DNA repair as well as the polyubiquitination of ATF5 in hepatocellular carcinoma cells and reported to be a pro-oncogenic and antioncogenic factor in context-dependent manner." (PMID 34224728, 2021). "Another interesting property for ATF5 in cancer is seen in hepatocellular carcinoma where ATF5 appears to possess a tumor suppressor role." (PMID 29137451, 2017). "ATF5 was significantly upregulated in several RCC cell lines after DNA demethylation, indicating a potential tumor suppressor role for ATF5 in RCC, perhaps similar to the role of ATF5 in hepatocellular carcinoma." (PMID 29137451, 2017). "The transcription factor, ATF5 binds to the cAMP response element (CRE) on cAMP inducible promoters and regulates several hepatic specific enzymes and its loss accompanies hepatic carcinomas." (PMID 20140224, 2010). "The only exception appears to be hepatocellular carcinoma cells, which express lower levels of ATF5 than normal liver cells; this discrepancy may be due to epigenetic silencing of ATF5 in hepatocellular carcinoma cells through promoter methylation." (PMID 21311102, 2010).
lung carcinoma (8 papers, 2015 to 2025). "Similar to those studies, here we show that stiff ECMs cause ATF5 to localize to the nuclei, from where it induces the proliferation of pancreatic and lung cancer cells." (PMID 40124511, 2025). "We have previously reported that ATF5 triggers proliferation, invasion, and irradiation resistance in lung cancer cells." (PMID 40124511, 2025). "We previously showed that transcriptional activity of the cAMP response element (CRE), downstream, is suppressed by ATF5 in lung cancer cells." (PMID 40124511, 2025). "We propose that ATF5 shows potential as a potent therapeutic target in tumors, with particular reference to stiff cancers, such as pancreatic and lung cancers." (PMID 40124511, 2025). "In this study, we revealed that ECM stiffness regulates the nuclear localization of ATF5 in pancreatic and lung cancer cells." (PMID 40124511, 2025). "The mechanism proposed by the authors to the shift in morphology was ATF5-mediated expression of integrin-β1 and integrin-α2 (which was reduced in ATF5-KD lung cancer cells)." (PMID 28785242, 2017). "This, together with an enhanced growth rate in vitro and in vivo of ATF5-transfected cells, suggests ATF5 promotes cell cycle progression and growth of lung carcinomas." (PMID 29137451, 2017). "It would be interesting to know if the expression levels of ATF5 in the ATF5-transfected A549 cells in this study are comparable to expression levels in clinical lung carcinoma samples." (PMID 29137451, 2017). "We next investigated the relationship between the expression of ATF5 and the prognosis of lung cancer patients." (PMID 25682872, 2015). "ATF5 overexpression promotes radio-resistance in lung cancer cells." (PMID 33640883, 2021). "Therefore, ATF5 is suggested to facilitate lung cancer development by promoting cellular proliferation and radioresistance while also being associated with poorer patient prognosis." (PMID 29137451, 2017). "Though this is intriguing, the role that ATF5 plays in promoting LKB1/STK11 mutant lung carcinomas is unknown." (PMID 29137451, 2017). "We demonstrated that ATF5 expression is correlated with poor prognosis of lung cancer." (PMID 25682872, 2015). "In addition, ATF5 has been found to be highly expressed in irradiation-tolerant lung cancer cells than in non-irradiated lung cancer cells, with such high expression being linked to enhanced proliferation and invasion of these cells." (PMID 40124511, 2025). "More ATF5 was localized in the nuclei of pancreatic cancer cells (KP4, AsPC1, and SUIT2) and lung cancer cells (A549) cultured on stiff ECMs (collagen-coated glass dishes) than that in those cultured on soft ECMs (collagen gels);." (PMID 40124511, 2025). "Here, we show that activating transcription factor 5 (ATF5), highly expressed in tumors, is activated by ECM stiffness and promotes the proliferation of cancer cells, including that of pancreatic cancer cells and lung cancer cells." (PMID 40124511, 2025).
diabetes (7 papers, 2017 to 2024). "Based on ChIP analysis, ATF5 has been proven to be the downstream target of pancreatic duodenal homeobox-1 (Pdx1), which is an important pathogenic gene in diabetes." (PMID 37095454, 2023). "In the early stages of diabetes, activating transcription factor 5 (ATF5) can exert a protective effect through the mtUPR." (PMID 39164792, 2024). "ATF5 is a downstream target gene of pancreatic and duodenal homeobox 1 (Pdx1), which is a key pathogenetic factor of diabetes." (PMID 37095454, 2023). "Our results are similar to those of previous reports showing that the deficiency of the genes induced by ATF4, such as Eif4ebp1 and Atf5, exacerbated hyperglycemia in the mouse models of diabetes." (PMID 34547510, 2021). "ATF5 might be involved in the developmental pathway of diabetes by regulating pancreatic β cell survival during cellular stresses and metabolic homeostasis." (PMID 35806136, 2022). "It remains to be determined whether other m.3243A > G-associated pathological phenotypes such as diabetes, deafness, and other symptoms in MELAS could also be ameliorated by ATF5 targeted inhibition." (PMID 34262025, 2021). "Overall, these findings indicate that ATF5 plays a critical role in regulating β-cell survival in response to ER stress and indicates that ATF5 may contribute to β-cell dysfunction in diseases such as diabetes mellitus." (PMID 29137451, 2017).
neuroblastoma (7 papers, 2004 to 2025). Neuroblastoma (NB) is the most common solid, extracranial childhood tumor. "Here, we show that ATF5 is highly expressed in patients with stage 4 high-risk neuroblastoma, with increased expression correlating with a poorer prognosis." (PMID 38014922, 2023). "To investigate the role of ATF5 role in neuroblastoma, we performed loss-of-function studies using two independent Dox-inducible pTRIPZ lentiviral short hairpin RNAs (shRNA) targeting ATF5." (PMID 38014922, 2023). "Here, we show that loss of ATF5 leads to neuroblastoma cell death." (PMID 38014922, 2023). "A recent study has linked ATF5 with neuroblastoma cell survival." (PMID 38014922, 2023). "In conclusion, our study identified ATF5 as a promoter of neuroblastoma metastasis and CP-d/n-ATF5 as an antimetastatic therapeutic agent with the potential to improve the clinical outcomes of metastatic neuroblastoma." (PMID 38014922, 2023). "Our study identified ATF5 as a metastasis promoter and CP-d/n-ATF5 as a potential antimetastatic therapeutic agent for neuroblastoma." (PMID 38014922, 2023). "ATF5 modulation in multiple neuroblastoma cell lines altered anchorage-independent survival in vitro and in vivo, influencing their metastasizing ability." (PMID 38014922, 2023). "Downregulation of PRMT1 in neuroblastoma leads to decreased expression of H4R3me2a enrichment at ATF5 promoter and inhibits tumor cell growth." (PMID 37143582, 2023). "Recent studies have identified the transcription factors CEBPB and CEBPD as CP-dn-ATF5 targets, suggesting they are also potential targets for neuroblastoma." (PMID 38014922, 2023). "Downregulation of PRMT1 expression in neuroblastoma results in reduced activity of the prosurvival factor ATF5 and inhibits tumor cell growth." (PMID 37143582, 2023). "This study shows that resistance to anoikis in neuroblastoma is mediated by ATF5 and offers a rationale for targeting ATF5 to treat metastatic neuroblastoma." (PMID 38014922, 2023). "We identified the proapoptotic BCL-2 modifying factor (BMF) as a critical player in ATF5-regulated neuroblastoma anoikis." (PMID 38014922, 2023). "Using cell culture models and intrarenal spontaneous and intracardiac experimental metastasis models, we identified ATF5 as a critical regulator of neuroblastoma growth and metastasis." (PMID 38014922, 2023). "Functionally, ATF5 depletion significantly reduced xenograft tumor growth and metastasis of neuroblastoma cells to the bone marrow and liver." (PMID 38014922, 2023). "The study has shown that inhibition of protein arginine methyltransferases 1 (PRMT1) induces apoptosis of human neuroblastoma cells and that ATF5 acts as a downstream effector of PRMT1-mediated survival signaling." (PMID 38014922, 2023). "Therapeutically, we showed that a cell-penetrating dominant-negative ATF5 peptide, CP-d/n-ATF5, inhibits neuroblastoma metastasis to the bone marrow and liver by inducing anoikis sensitivity in circulating tumor cells." (PMID 38014922, 2023). "Our studies identified CP-d/n-ATF5 as an effective therapeutic agent with antimetastatic efficacy and supported the clinical testing of such peptides in patients with neuroblastoma." (PMID 38014922, 2023). "ATF5 is significantly down-regulated in PRMT1-depleted cells, and the over-expression of ATF5 can rescue the neuroblastoma cells from PRMT1 depletion-induced apoptosis." (PMID 35806136, 2022). "We demonstrated that ATF5 promotes the metastasis of neuroblastoma cell lines in vivo." (PMID 38014922, 2023). "There have been no published reports to date linking ATF5 to neuroblastoma tumorigenesis, even though the potential role of ATF5 in neuroblastoma cell survival has been implicated in recent conference abstracts." (PMID 32415090, 2020). "We report here, to our knowledge, PRMT1 as a novel regulator of ATF5 in neuroblastoma." (PMID 32415090, 2020).
neuroblastoma (continued). "ATF5 is a transcription factor of the basic-leucinezipper family that has been suggested to modulate neurogenesis making it potentially interesting in the biology of the neuroblastoma cells." (PMID 15544702, 2004). "Therefore, it is tempting to speculate that ATF5 may act as a general downstream effector of PRMT1-mediated survival signaling in neuroblastoma." (PMID 32415090, 2020). "In the case of neuroblastoma cells, we did not observe differentiation upon ATF5 depletion or CP-dn-ATF5 treatment, but rather the onset of apoptosis/anoikis." (PMID 38014922, 2023). "In vitro, under adherent conditions, CP-d/n-ATF5 dose-dependently inhibited the growth of a panel of neuroblastoma cell lines, both MYCN-amplified and MYCN-non-amplified." (PMID 38014922, 2023). "Moreover, ATF5 is a down-stream effector of protein arginine methyltransferase 1 (PRMT1), which is an essential regulator of neuroblastoma cell survival." (PMID 35806136, 2022). "Yamashiro’s group found that suppression of ATF5 activity with an inhibitory peptide led to a concentration-dependent decrease of cell viability and increase of cell apoptosis in a panel of human neuroblastoma cell lines regardless of MYCN amplification." (PMID 32415090, 2020). "Therefore, we speculate that CP-d/n-ATF5-induces the depletion of ATF5, leading to increased BMF, resulting in anoikis of neuroblastoma cells in suspension culture and the blood circulation of mice." (PMID 38014922, 2023). "PRMT1 promotes cell survival through epigenetic activation of the prosurvival factor ATF5, thus providing a new mechanistic link between overexpression of PRMT1 and compromised apoptotic pathway, a malignant phenotype characteristic of a large number of cancers, including neuroblastoma." (PMID 32415090, 2020). "We found that ATF5 knockdown reduced the expression of BCL-2 and MCL-1, but not of BMF, in adherent neuroblastoma cells." (PMID 38014922, 2023). "In neuroblastomas with MYCN amplification or high MYCN levels without MYCN amplification, the positive regulatory loop of the MYCN-PRMT1 axis may promote a MYCN-driven oncogenic program whereas PRMT1-mediated activation of ATF5 may lead to enhanced survival." (PMID 32415090, 2020).